SHISA3 (shisa family member 3)
Description:
Plays an essential role in the maturation of presomitic mesoderm cells by individual attenuation of both FGF and WNT signaling.
Synonyms: hShisa3
Tractability: Antibody: UniProt predicts a signal peptide or a membrane-spanning region.
Gene: Protein-coding gene on chromosome 4 (42,397,488 to 42,402,487, forward strand). Ensembl gene ENSG00000178343.
Subcellular location: Endoplasmic reticulum membrane
Subcellular location (Human Protein Atlas): Cytosol; Lipid droplets
Gene Ontology:
Molecular function: protein binding
Cellular component: endoplasmic reticulum membrane
Genetic constraint (gnomAD): Loss-of-function variants: 15 observed, 16.62 expected, observed/expected ratio (o/e) 0.9, 90% interval 0.6 to 1.39. The upper end of that interval is the gene's LOEUF score, 1.39, which puts it in group 5 of 6, group 1 being the genes least tolerant of losing a copy. Missense variants: 327 observed, 304.69 expected, observed/expected ratio (o/e) 1.07, 90% interval 0.98 to 1.18. Synonymous variants: 145 observed, 131.64 expected, observed/expected ratio (o/e) 1.1, 90% interval 0.96 to 1.26.
Homologues: Orthologues: chimpanzee SHISA3 (99% identical), macaque SHISA3 (99% identical), pig SHISA3 (96% identical), guinea pig SHISA3 (93% identical), mouse Shisa3 (92% identical), rat Shisa3 (92% identical), dog SHISA3 (87% identical), tropical clawed frog shisa3 (70% identical), zebrafish shisa3 (64% identical). Paralogues in human: SHISA2 (49% identical), SHISA4 (19% identical), SHISAL1 (16% identical), SHISAL2A (13% identical), SHISAL2B (12% identical).
Diseases named in the same sentence as SHISA3 in open-access papers:
SHISA3 is named in the same sentence as 16 diseases in open-access papers, as found by Europe PMC text mining. Sharing a sentence is not in itself a finding about the gene and the disease. The quoted sentences say what the papers report.
lung carcinoma (7 papers, 2017 to 2025). "Higher expression of SHISA3 in TAMs is associated with better overall survival in lung cancer patients." (PMID 39054639, 2024). "It further found that higher expression of SHISA3 in antitumoral TAMs is associated with better overall survival in lung cancer patients." (PMID 39054639, 2024). "The results showed that higher expression of SHISA3 correlated with a better prognosis for diverse cancers, including breast cancer, lung cancer, and pancreatic cancer." (PMID 39054639, 2024). "Previously, SHISA3 has been described as an antagonist of Wnt/β-catenin pathway in lung cancer by reducing Wnt receptors, accelerating β-catenin degradation and ultimately suppressing Wnt-mediated gene expression." (PMID 32692756, 2020). "Previous study revealed that SHISA3 plays a role as a tumor suppressor in lung cancer, by inhibiting the Wnt/β-catenin signaling pathway in lung adenocarcinoma cells." (PMID 32584890, 2020). "SHISA3 was a novel tumor suppressor identified in lung cancer, and was found to be epigenetically inactivated in a substantial fraction of patients with colorectal cancer." (PMID 28716111, 2017). "Notably, higher expression of SHISA3 in anti-tumor TAMs is correlated with better OS in lung cancer patients." (PMID 41417432, 2025). "We also showed that the higher expression of SHISA3 in TME or TAMs inhibits the progression of lung cancer patients and may promote CD8+ T cell infiltration." (PMID 39054639, 2024). "Very recently, SHISA3 was described as tumor suppressor gene in lung cancer." (PMID 32692756, 2020). "The human shisa family member 3 (SHISA3) is located on chromosome 4p13 and was recently discovered to be a tumor suppressor gene, which suppresses the tumorigenesis, invasion, and metastasis of lung cancer through the degradation of β-catenin of the Wnt signaling pathway." (PMID 28299336, 2017).
colorectal cancer (6 papers, 2017 to 2026). A primary or metastatic malignant neoplasm that affects the colon or rectum. "The second group features R-spondin 3 (Rspo3), collagen and calcium binding EGF domains 1 (Ccbe1), and Shisa homolog 3 (Shisa3) genes, potentially relevant to colorectal cancer and therapy." (PMID 41262530, 2026). "SHISA3 gene, hypermethylated in our study, was epigenetically inactivated in the colorectal cancer cell line." (PMID 32244494, 2020). "Later on, SHISA3 silencing was also observed in colorectal cancer as a consequence of promoter hypermethylation." (PMID 32692756, 2020). "The SHISA3 methylation frequency in our study was comparable to previous reports in colorectal cancer and laryngeal squamous cell carcinoma." (PMID 32692756, 2020). "Recent reports have demonstrated that hypermethylation of the SHISA3 promoter region is a common event in colorectal cancer tissues and cell lines, and can serve as an independent predictor of poor overall survival for colorectal cancer patients." (PMID 28299336, 2017). "Subsequently, promoter region of SHISA3 was found to be hypermethylated in colorectal cancer, laryngeal squamous cells carcinoma and nasopharyngeal carcinoma suggesting the possibly ubiquitous role that SHISA3 may play in carcinogenesis." (PMID 32692756, 2020).
lung adenocarcinoma (3 papers, 2019 to 2024). A carcinoma that arises from the lung and is characterized by the presence of malignant glandular epithelial cells. "If SHISA3 regulates Wnt/β-catenin signaling pathway in muscle cells in the same way as lung adenocarcinoma cells, expression of SHISA3 should have shown positive correlations with beef quality traits." (PMID 32584890, 2020). "Shisa3 was identified as an independent OS factor for lung adenocarcinoma by univariate and multivariate Cox regression analyses." (PMID 31801598, 2019).
breast carcinoma (2 papers, 2020 to 2024). "Association between SHISA3 hypermethylation and clinicopathological parameters of breast cancer patients." (PMID 32692756, 2020). "The current study is the first to describe the hypermethylation and silencing of SHISA3 gene in breast cancer." (PMID 32692756, 2020). "Methylation array analysis of TCGA-BRCA datasets indicated hypermethylation of the SHISA3 gene in breast cancer specimens ILBC (75%), IDBC (81%) and IBC (70%) as compared to normal breast tissue." (PMID 32692756, 2020). "Taken together, our results indicated that promoter methylation is a major mechanism of SHISA3 silencing in breast cancer cells." (PMID 32692756, 2020). "The re-gain of SHISA3 expression in breast cancer cells after 5’-aza, 2-deoxycytidine confirms that hypermethylation is responsible for the inactivation of this gene in breast cancer." (PMID 32692756, 2020). "Altogether, our study for the first time explored the epigenetic silencing of SHISA3 rendering in breast cancer and has shown that SHISA3 silencing via promoter hypermethylation is a frequent event in BC." (PMID 32692756, 2020). "The clinicopathological data revealed that SHISA3 epigenetic inactivation is a crucial episode in breast cancer." (PMID 32692756, 2020). "Data for transcriptome analysis was bulk downloaded to include multiple breast cancer types from various studies and filtered for corresponding SHISA3 probes to analyze it expression." (PMID 32692756, 2020). "Furthermore, our data revealed that the ectopic expression of SHISA3 significantly reduces the ability of breast cancer cells to proliferate and migrate, beaconing its role as a tumor suppressor in breast cancer." (PMID 32692756, 2020).
laryngeal squamous cell carcinoma (2 papers, 2017 to 2020). A squamous cell carcinoma that arises from the larynx. "Subsequently, epigenetic inactivation of SHISA3 was also described in laryngeal squamous cell carcinoma and nasopharyngeal carcinoma." (PMID 32692756, 2020).
lymph node metastasis (2 papers, 2017 to 2020). "The results show that SHISA3 promoter methylation is significantly associated with histological grade (P = 0.02), clinical stage (P = 0.02), tumor stage (P = 0.05), and lymph node metastasis (P = 0.03)." (PMID 28299336, 2017). "We also investigated the connection between SHISA3 methylation levels and clinicopathological parameters of BC patients such as age, tumor size, histological grade, tumor stage and lymph node metastasis." (PMID 32692756, 2020). "In our data, significant correlation was found only between SHISA3 methylation and histological grade (P = 0.037) and lymph node metastasis (P = 0.016)." (PMID 32692756, 2020). "The association between SHISA3 promoter methylation status and the clinicopathological parameters of the LSCC patients, including age, gender, smoking behavior, histological grade, clinical stage, tumor stage, and lymph node metastasis, was assessed." (PMID 28299336, 2017).
nasopharyngeal carcinoma (2 papers, 2020). A carcinoma arising from the nasopharyngeal epithelium. "Accordingly, SHISA3 is downregulated in various tumor types, including nasopharyngeal carcinoma (NPC) in which the SHISA3 promoter hypermethylation correlates with the SHISA3 ability to suppress the NPC in vitro invasion and in vivo lymph node metastasis." (PMID 32806509, 2020).
neuroblastoma (1 paper, 2019). Neuroblastoma (NB) is the most common solid, extracranial childhood tumor. "Overall, we found that downregulation of 7 genes (Crb1, Lrrc9, Rcn1, Rtl1, Shisa3, Six6, St18) and upregulation of 2 genes (C1ql3, Slc18A1), are strongly predictive of favorable neuroblastoma outcome, consistent with delayed tumor development in Th-MYCN/Casp2−/− mice." (PMID 30670683, 2019).
Sepsis (1 paper, 2024). Sepsis is defined as life-threatening organ dysfunction caused by a dysregulated host response to infection. "To further confirm the role of Shisa3 induced macrophage M1 polarization in acute inflammation, we established LPS‐sepsis mouse model with WT or Shisa3‐KO mice." (PMID 39054639, 2024). "In the mouse model of LPS induced sepsis, the expression of Shisa3 in bone marrow cells was greatly upregulated." (PMID 39054639, 2024).
tumor (14 papers, 2017 to 2025). "Some of them are known to affect cellular growth/proliferation: SHISA3 is a known tumor suppressor, APBB2 plays a role in Alzheimer’s disease and the cell cycle, and UCHL1 promotes cellular proliferation in cancer." (PMID 40930101, 2025). "Other studies have shown that the tumor suppressor gene SHISA3 can promote M1 polarization of macrophages and act on tumor cells to limit tumor growth." (PMID 40131539, 2025). "We further explored the role of SHISA3 in macrophage phagocytosis of tumor cells, and flow cytometry results showed that Shisa3 overexpression in BMDMs attenuated tumor cells escape from macrophage phagocytosis." (PMID 39054639, 2024). "In this model, combination therapy with MPLA and PD‐1 antibody suppressed tumor growth, which was largely abolished by Shisa3 knockout." (PMID 39054639, 2024). "Due to the low expression of Shisa3 at basal level, we found that there is no statistical significance between the two groups, although the tumor growth in Shisa3‐KO mice showed an accelerating trend." (PMID 39054639, 2024). "Our findings indicate that Shisa3 not only promotes the repolarization of TAMs into an anti‐tumor phenotype but also enhances T‐cell activation, consequently converting “cold” tumors into “hot” tumors." (PMID 39054639, 2024). "Since a major activity of antitumoral TAMs is to promote antitumor immune responses and inhibit tumor progression, we then tested the overexpression of SHISA3 in BMDM on CD8+ T cell‐mediated antitumor immunity." (PMID 39054639, 2024). "Next, we performed a subcutaneous tumor formation experiment in WT and Shisa3‐KO mice to evaluate the antitumor effects of this gene." (PMID 39054639, 2024). "We found that overexpression of SHISA3 in macrophages polarized them to the antitumoral type, thereby curbing tumor growth through enhancing phagocytosis of tumor cells and CD8+ T cell‐mediated anti‐tumor immunity." (PMID 39054639, 2024). "Multiple studies have shown that SHISA3 significantly inhibits tumor growth, reverses drug resistance, and inhibits tumor stem cell characteristics." (PMID 39054639, 2024). "To address the potential role of SHISA3 in TAMs during tumor development, we first try to overexpress Shisa3 in macrophages." (PMID 39054639, 2024). "In all of these studies, tumor suppressor nature of SHISA3 and its hypermethylation was found to be crucial in the diagnosis and prediction of the clinical outcome of various cancer types." (PMID 32692756, 2020). "We also found that the proliferation and migration abilities of BC cells were inhibited due to the ectopic expression of SHISA3 which hints at its role as a tumor suppressor gene." (PMID 32692756, 2020). "Very recently, epigenetic silencing of SHISA3, an antagonist of β-catenin, has been reported in various types of tumor." (PMID 32692756, 2020). "Taken together, our findings for the first time reveal epigenetic silencing and tumor suppressing role of SHISA3 in BC." (PMID 32692756, 2020). "Shisa3 was revealed as a tumor suppressor and a new insight for tumor prognosis and therapy; it could be a biomarker for patients suffering from chronic lymphocytic leukemia, regardless of whether they could benefit from lenalidomide treatment." (PMID 34638298, 2021). "The results of these experiments convincingly support the hypothesis that SHISA3 act as a tumor suppressor gene in BC." (PMID 32692756, 2020). "Interestingly, the results indicate that SHISA3 promoter methylation is more frequently observed in poorly differentiated, lymph node metastasis, and advanced clinical stages, as well as advanced tumor invasion LSCC patients." (PMID 28299336, 2017). "Herein, we found that 5 genes (Shisa3, PADI1, LRP2, ANGPTL4 and ALOX15B) were upregulated and 4 genes (CXCL9, ADAMDEC1, SCGB1A1/CC10, HLA-G) were downregulated in PR tumor tissues compared to SD tumor tissues." (PMID 31801598, 2019).
tumor (continued). "Knockout Shisa3 in macrophages inhibits its phagocytic effect on tumor cells with or without LPS stimulation." (PMID 39054639, 2024). "Nevertheless, the tumor suppressing action and promoter methylation of SHISA3 has not been fully investigated yet in other types of cancer including BC." (PMID 32692756, 2020).
cancer (7 papers, 2017 to 2025). A tumor composed of atypical neoplastic, often pleomorphic cells that invade other tissues. "Local delivery of mRNA encoding Shisa3 enables cancer immunotherapy by reprogramming TAMs toward an antitumoral phenotype, thus enhancing the efficacy of programmed cell death 1 (PD‐1) antibody." (PMID 39054639, 2024). "Two of the CaREs identified to regulate SHISA3 by TESLA-seq (SHISA3 promoter CaRE_790 and CaRE_816) intersect with the somatic risk variants found in cancer." (PMID 40930101, 2025). "Enforced expression of Shisa3 in TAMs enables cancer immunotherapy by NF‐κB‐mediated reprogramming of TAMs toward an antitumoral phenotype, thus enhances the efficacy of immune checkpoint blockade (ICB) therapy." (PMID 39054639, 2024). "We further checked if the expression of SHISA3 in TAMs would affect disease progression in cancer patients." (PMID 39054639, 2024). "By using the ESTIMATE algorithm to develop a gene signature based on the estimation of stromal and immune cells in malignant tumor tissues, we found a positive correlation between the expression of SHISA3 and immune scores in several databases." (PMID 39054639, 2024). "Taken together, the findings describe the role of SHISA3 in reprogramming TAMs that ameliorate cancer immunotherapy." (PMID 39054639, 2024). "Since SHISA3 expression is dysregulated in multiple cancers, the present study aimed at investigating the status of its expression in BC as well as its potential role in BC pathogenesis." (PMID 32692756, 2020). "Taken together, SHISA3 promises to be a therapeutic target for cancer immunotherapy." (PMID 39054639, 2024). "This study identified SHISA3 as a valuable therapeutic gene for cancer immunotherapy." (PMID 39054639, 2024). "Similarly, hypermethylation of SHISA3, KCNA3, NPY, and hypomethylation of NUMB, BST2, MAPK13 promoters, which have previously been implicated in other cancers, robustly separate normal and GBC-OSCC samples." (PMID 37245006, 2023). "SHISA3 expression was retrieved in both BC cell lines, indicating that hypermethylation of SHISA3 promoter was responsible for the silencing of this gene in BC, like many other types of cancer." (PMID 32692756, 2020). "Local delivery of Shisa3 mRNA or AAV‐Shisa3 transducted macrophages showed a superior effect when combined with PD‐1 blockade, suggesting that SHISA3 is a novel target for cancer immunotherapy." (PMID 39054639, 2024). "For TAMs are the major components of the TME in LUAD and the positive correlation between SHISA3 level and M1 macrophage infiltration in LUAD is the most significant among these cancers, we next explored the clinical significance of SHISA3 in LUAD patients." (PMID 39054639, 2024). "A positive correlation between SHISA3 and CD8+ T cells was also shown in most types of these cancers." (PMID 39054639, 2024). "Shisa3 has been reported to accelerate the degradation of β-catenin in the Wnt signaling pathway, which regulates CSC maintenance in diverse types of cancer." (PMID 31801598, 2019).
SHISA3 also shares sentences with these, for which no sentence is quoted: non-small cell lung carcinoma (2 papers); Obesity (1); oral cancer (1); pancreatic cancer (1); prostate carcinoma (1).